CGAS (cyclic GMP-AMP synthase)
Diseases named in the same sentence as CGAS in open-access papers (continued):
Sharing a sentence is not in itself a finding about the gene and the disease.
ischemic stroke (31 papers, 2020 to 2026). A stroke disorder caused by obstruction of blood flow to the brain, due to thrombotic (local blood clot formation) or embolic (due to a blood clot or other material traveling from another site) event. "The cGAS-STING pathway is closely associated with the initiation of the neuroinflammatory response in ischemic stroke." (PMID 37915571, 2023). "This section underscores the importance of the cGAS-STING pathway-mediated chronic inflammatory response in the risk factors linked to ischemic stroke." (PMID 37915571, 2023). "Cellular DNA damage caused by ischemic stroke is closely associated with in activating the cGAS-STING pathway." (PMID 37915571, 2023). "A recent preclinical study demonstrated that pharmacological inhibition of cGAS following ischemic stroke in young mice reduced neuroinflammation and tissue loss." (PMID 34504493, 2021). "Recent data showed that targeting DNA sensor cyclic GMP-AMP synthase (cGAS) or NETs potentially benefitted thrombolytic therapy in patients with ischemic stroke by decreasing tPA-associated hemorrhage." (PMID 34947883, 2021). "By far, the precise mechanism by which the cGAS-STING pathway is implicated in ferroptosis during ischemic stroke remains unclear." (PMID 37915571, 2023). "Accordingly, DNase1-mediated reversal of microglia activation, cerebrovascular protection and anti-hemorrhagic effects after ischemic stroke were abolished by co-administration of the cGAS product cGAMP, whereas cGAS deficiency rescued t-PA-associated BBB disruption and cerebral hemorrhage." (PMID 37550658, 2023). "Finally, it suggests that intervention targeting the cGAS-STING pathway may serve as promising therapeutic strategies for addressing neuroinflammation associated with ischemic stroke." (PMID 37915571, 2023). "cGAS has been identified as a critical cytosolic DNA sensor that detects dsDNA in a length-dependent while the sequence-independent manner, which is closely associated with neuroinflammation in the animal models of ischemic stroke, amyotrophic lateral sclerosis, and traumatic brain injury." (PMID 35689216, 2022). "In ischaemic stroke, cGAS-STING silencing, AAV-NeuroD1-mediated neuronal reprogramming, and delivery of neurotrophic factors, including VEGF and BDNF, extend the therapeutic window well beyond reperfusion." (PMID 42193469, 2026). "Conversely, evidence shows that the cGAS/STING/IRF3 pathway exhibits dual roles in ischemic stroke, potentially mediating either neuroinflammatory apoptosis or functional recovery depending on activation context." (PMID 41471264, 2025). "For instance, during ischemic stroke, brain ischemia leads to the release of double-stranded DNA (dsDNA) into the cytoplasm, activating the cyclic GMP-AMP synthase (cGAS) signaling pathway and the AIM2 inflammasome in microglia." (PMID 39994107, 2025). "In current ischemic stroke-reperfusion injury models, cGAS-STING inhibitors have shown promising efficacy." (PMID 39741707, 2024). "RU.521, a cGAS inhibitor, has been demonstrated to improve motor function and reduce infarct volume in rat and mouse models of ischemic stroke induced by middle cerebral artery occlusion." (PMID 39741707, 2024). "When using cGAS KO mice as an ischemic stroke animal model, addressing potential extracerebral interferences becomes a concern." (PMID 37915571, 2023). "During ischemic stroke, mtDNA is released into the cytoplasm, which activates cGAS/STING signaling in microglia." (PMID 37354378, 2023). "This suggests that Activin A holds promise as a potential therapeutic agent for ischemic stroke by mitigating cGAS-STING-dependent neuronal autophagy." (PMID 37915571, 2023). "It is noteworthy that both the knockout cGAS mice and the use of cGAS inhibitors appear to suppress the neuroinflammatory response in ischemic stroke." (PMID 37915571, 2023).
ischemic stroke (continued). "In tissue plasminogen activator-induced brain hemorrhage after ischemic stroke, activation of the cGAS-STING pathway resulting from NET formation accounted for the deterioration of cerebrovascular integrity." (PMID 37626060, 2023). "A plethora of studies have been devoted to intervening in RCD to extend the thrombolytic window for the management of ischemic stroke, and some of these studies have demonstrated interactions between the cGAS-STING pathway and multiple RCDs." (PMID 37915571, 2023). "Presently, there are surge in research on the involvement of the cGAS-STING pathway mediating neuroinflammation in the context of ischemic stroke." (PMID 37915571, 2023). "Accordingly, the cGAS-STING pathway represents a promising avenue for further exploration in immunotherapy for ischemic stroke." (PMID 37915571, 2023). "Recent studies have confirmed a complex relationship between oxidative stress in ischemic stroke and the cGAS-STING pathway." (PMID 37915571, 2023). "It is highly conceivable that the cGAS-STING pathway involves several aspects of ferroptosis in ischemic stroke." (PMID 37915571, 2023). "Therapeutical Potential of Targeting the cGAS-STING Pathway against Neuroinflammation in Ischemic Stroke." (PMID 37915571, 2023). "This strongly suggests that the cGAS-STING pathway can serve as a potential target for intervening in the neuroinflammatory response of ischemic stroke." (PMID 37915571, 2023). "In the context of ischemic stroke, the DNA backbone of NETs has the ability to function as a ligand, thereby activating cGAS and subsequently inducing microglia activation and neuroinflammation." (PMID 37915571, 2023). "This comprehensive review aims to provide an overview of the importance of the cGAS-STING pathway in ischemic stroke, emphasizing the neuroinflammatory responses resulting from its over-activation." (PMID 37915571, 2023). "Initially, it examines how various risk factors and pre-disease mechanisms such as metabolic dysfunction and senescence (e.g., hypertension, hyperglycemia, hyperlipidemia) affect the cGAS-STING pathway in relation to ischemic stroke." (PMID 37915571, 2023). "One study in vivo and in vitro observed that microglia cells were quickly activated following ischemic stroke (IS), and the cGAS–STING signaling pathway in the microglia was triggered to encourage the development of a pro-inflammatory microenvironment." (PMID 36618820, 2022). "The cyclic GMP-AMP synthase–stimulator of interferon gene (cGAS–STING) axis is a cytoplasmic double-stranded DNA (dsDNA) sensing pathway has recently emerged as a crucial mediator of neuroinflammation in ischemic stroke." (PMID 35689216, 2022). "Middle cerebral artery occlusion (MCAO), a murine model of ischemic stroke, increases the release of dsDNA into the cytosol and initiates inflammatory responses by activating cGAS." (PMID 34631213, 2021). "This study focuses on the inflammatory cascade on double‐strand DNA (dsDNA) recognition and highlights the possibility of inhibiting dsDNA‐sensing cyclic GMP‐AMP synthase (cGAS) for treatment of ischemic stroke." (PMID 32239625, 2020). "This study aimed to investigate the function and regulatory mechanism of cGAS in I/R-induced neuroinflammation and brain injury, and to identify possible strategies for the treatment of ischemic stroke." (PMID 32863951, 2020). "The cGAS-STING pathway is closely associated with neuroinflammation, which has been demonstrated in acute brain injuries, such as traumatic brain injury, subarachnoid hemorrhage, and ischemic stroke." (PMID 38637346, 2024). "The regulation of cGAS expression in microglia has the potential to affect the activation of microglia and the downstream pro-inflammatory cytokines, consequently influencing the neuroinflammatory response in ischemic stroke." (PMID 37915571, 2023). "In a study on ischemic stroke, the inhibition of cGAS improved ischemic brain injury." (PMID 37354378, 2023).
ischemic stroke (continued). "We posit that the aberrant accumulation of unfolded proteins in ischemic stroke may likely be attributed to the dysregulation of the cGAS-STING pathway." (PMID 37915571, 2023). "Growing evidence suggests that the Cyclic GMP-AMP synthase (cGAS)- Stimulator of interferon genes (STING) pathway, a component of innate immunity, is closely associated with microglia activation, neuroinflammation, and regulated cell death in ischemic stroke." (PMID 37915571, 2023). "Preventing cGAS-STING activation after ischemic stroke helps alleviate neuroinflammatory burden." (PMID 37502677, 2023). "Additionally, as the primary site of oxidative respiration, mitochondrial damage during ischemic stroke also leads to increased cytoplasmic mtDNA, thereby activating cGAS." (PMID 37915571, 2023). "Taken together, this review concludes that targeting the microglia cGAS-STING pathway may shed light on the exploration of new therapeutic strategies against ischemic stroke." (PMID 37915571, 2023). "Hence, regulating the activation of the cGAS-STING pathway in microglia is critical in regulating neuroinflammatory responses during ischemic stroke." (PMID 37915571, 2023). "Therefore, inhibition of NETs or cGAS will provide a new avenue to block tPA thrombolysis upon ischemic stroke pathological condition." (PMID 35186921, 2022). "The cGAS–STING pathway has a significant function following ischemic stroke, as evidenced by an increasing number of studies, and modulation of this pathway may play a significant role in the treatment of ischemic stroke." (PMID 36618820, 2022). "In the ischemic stroke mice model, the NETs induced by activation of cGAS-STING and the subsequent type 1 interferon response contribute to tissue plasminogen activator (tPA)-associated hemorrhage, resulting in increased loss of cerebrovascular integrity and amplified blood–brain barrier damage." (PMID 35186921, 2022). "Inhibition of cGAS can attenuate neuroinflammation after ischemic stroke in mice." (PMID 35677585, 2022). "Collectively, these studies indicate that activation of the endogenous cGAS-STING cascade may be detrimental to the outcomes of ischemic stroke." (PMID 34631213, 2021). "Inhibition of dsDNA‐sensing cGAS is sufficient to suppress the overall neuroinflammatory response and may present a promising new therapeutic concept for ischemic stroke." (PMID 32239625, 2020). "Consequently, targeting the cGAS-STING pathway may offer a promising avenue for immunotherapy in treating ischemic stroke." (PMID 37915571, 2023). "A previous study demonstrated that NET formation was upregulated in brain parenchyma in mice subjected to ischemic stroke and NETs as the main source circulating ds-DNA, could contribute to neuroinflammation and blood-brain barrier disruption via the cGAS/STING pathway." (PMID 37143681, 2023). "Increasing evidence has shown that the cGAS-cGAMP-STING signaling axis plays a key role in numerous stroke diseases, such as ischemic stroke and sinus thrombosis." (PMID 38169382, 2024). "The cGAS-STING pathway is involved in several conditions, such as acute kidney injury, Parkinson’s disease, and ischemic stroke." (PMID 38169382, 2024). "The role of cGAS-STING in neuroinflammation, and particularly in ischemic stroke, brings both overlapping and distinct characteristics when compared to classical pathways, providing new insights into potential therapeutic approaches." (PMID 39741707, 2024). "In the context of ischemic stroke, damaged cells release mitochondrial and nuclear DNA into the cytoplasm, where it serves as a DAMP that activates cGAS-STING signaling." (PMID 39741707, 2024). "After an ischemic stroke, HDAC3 regulates the nuclear localization and acetylation of microglial p65, which enhances the activation of the cGAS-STING pathway and transcriptionally promotes the production of cGAS." (PMID 39649720, 2024).
ischemic stroke (continued). "In a mouse model of ischemic stroke, Activin A phosphorylates PKB via the PI3K-PKB pathway, which in turn PKB phosphorylates the S291 or S305 residue of mouse or human cGAS." (PMID 37915571, 2023). "This article comprehensively reviews the existing literature on the cGAS-STING pathway and its multifaceted relationship with ischemic stroke." (PMID 37915571, 2023). "Deletion of cGAS or HDAC3 in microglia attenuates neuroinflammation and brain injury in tMCAO mice, highlighting a novel therapeutic avenue for the treatment of ischemic stroke." (PMID 34631213, 2021). "Furthermore, the knockdown of cGAS in the cGAS‐STING signaling pathway was found to promote microglial M2 polarization and improve neuroinflammation and cognitive function in ischemic stroke." (PMID 38459658, 2024). "Although the precise mechanism by which the cGAS-STING pathway and AIM2 participate in the inflammatory reaction during ischemic stroke remains ambiguous, the interaction of downstream NF‐κB with GSDMD or type I IFN with AIM2 may be involved." (PMID 37915571, 2023). "Blocking cGAS with RU.521 suppressed the inflammatory cascade and NLRP3 inflammasome-mediated microglia pyroptosis, thereby exerting an anti-CVST effect and mitigating the occurrence of ischemic stroke." (PMID 37915571, 2023). "The bidirectional regulation of oxidative stress by the cGAS-STING pathway suggests a unique characteristic that has significant implications for innate immunity, enhancing its defensive efficacy against oxidative stress in ischemic stroke." (PMID 37915571, 2023). "Prior studies have demonstrated that cGAS/STING are upregulated after acute neural injury, and selective inhibition of cGAS or STING reduces neuroinflammation and promotes functional recovery in animal models of ischemic stroke and TBI." (PMID 34504493, 2021). "No studies have yet demonstrated whether cGAS KO induces numerous uncontrollable alterations in the immune system, potentially confounding ischemic stroke investigations." (PMID 37915571, 2023). "However, in these studies, cGAS was more concerned and explored in ischemic stroke, but there is no interfering targeting STING was performed." (PMID 35450066, 2022).
myocardial infarction (31 papers, 2018 to 2026). Gross necrosis of the myocardium, as a result of interruption of the blood supply to the area, as in coronary thrombosis. "Activation of the CGAS promotes macrophage transformation, whereas loss-of-function of CGAS provokes a reparative phenotype and enhances myocardial repair in the setting of coronary ligation in a mouse model of myocardial infarction." (PMID 40180542, 2025). "cGAS deficiency also protects against myocardial infarction-induced adverse ventricular remodeling and rupture and enhances tissue repair in the infarct region." (PMID 34659260, 2021). "Activation of the cGAS‐STING pathway has been associated with a number of CVDs, including atherosclerosis, aortic aneurysms, myocardial infarction, and hypertension." (PMID 40279334, 2025). "The Journal retracts the article “The cGAS-STING Pathway: A New Therapeutic Target for Ischemia–Reperfusion Injury in Acute Myocardial Infarction?” cited above." (PMID 41259155, 2025). "Accordingly, permanent coronary ligation in mice, a model of myocardial infarction, by releasing the self-DNA activates the CGAS-STING1 pathways, provoked phosphorylation of IRF3 and induced expression of the type I interferon response genes." (PMID 40180542, 2025). "Not surprisingly, therefore, the initial evidence of the activation of the CGAS-STING1 pathway in cardiovascular disease was observed in the setting of myocardial infarction." (PMID 40180542, 2025). "Many recent studies have revealed a regulatory role of the cGAS-STING signaling pathway in cardiovascular diseases (CVDs) such as myocardial infarction, heart failure, atherosclerosis, and aortic dissection/aneurysm." (PMID 38720328, 2024). "As a cytosolic DNA sensor, cGAS is activated robustly in myocardial infarction, triggering downstream events mediated by the STING cascade." (PMID 39695094, 2024). "Another study found that the cGAS–STING signaling pathway aggravated the proinflammatory response in a mouse model of myocardial infarction." (PMID 38525112, 2024). "During myocardial infarction, massive cell death activated the cGAS–STING pathway in macrophages, worsening the survival of mice." (PMID 39254994, 2024). "TY1, a synthetic non-coding RNA (ncRNA) bioinspired by small Y RNAs abundant in extracellular vesicles (EVs), decreases cGAS/STING activation in myocardial infarction and thereby attenuates inflammation." (PMID 39739013, 2024). "Myocardial infarction (MI) is accompanied by inflammatory and immune responses and results in massive cardiomyocyte death due to overactive cGAS/STING signaling." (PMID 37354378, 2023). "In atherosclerosis, diabetic cardiomyopathy, and myocardial infarction models, the cGAS-STING pathway is activated and downstream molecules are expressed." (PMID 37600809, 2023). "Recently, abnormal and disordered signalling of the cGAS-STING axis has been closely associated with various sterile inflammatory diseases, including heart failure, myocardial infarction, and cardiac hypertrophy." (PMID 37537600, 2023). "In animal experiments, on the 28th day after myocardial infarction modeling in mice, the H-151 treatment exerted a significant inhibitory effect on the cGAS-STING-IRF3 pathway and inflammatory responses, especially the type I IFN response." (PMID 37600809, 2023). "They demonstrate increased IFNβ1 expression and IRF3 phosphorylation and an increase in the expression levels of CXCL10, IRF7, STING, and cGAS after myocardial infarction." (PMID 34381828, 2021). "The cGAS-STING signaling pathway is activated following myocardial infarction by recognizing self-DNA derived from dead cells in the heart." (PMID 33633744, 2020). "Consistent with the pathogenic role of activation of the CGAS-STING1 pathway, deletion of the Mb21d1, Sting1, or Irf3 gene abrogated the induction of the interferon 1 response and improved survival and cardiac remodeling in a mouse model of myocardial infarction." (PMID 40180542, 2025).